HSD17B13 (hydroxysteroid 17-beta dehydrogenase 13)
Diseases named in the same sentence as HSD17B13 in open-access papers (continued):
Sharing a sentence is not in itself a finding about the gene and the disease.
diabetes (5 papers, 2021 to 2025). "Conversely, among patients with high‐risk factors of HCC, such as diabetes and hypertension, the HSD17B13 A/A genotype was associated with an increased risk of HCC." (PMID 37644826, 2023). "In a previous study, multivariate analysis showed that age, male sex, diabetes, platelet count, gamma‐glutamyltransferase and albumin levels, and the 7‐SNP genetic risk score, including PNPLA3 and HSD17B13, are independent risk factors of HCC development." (PMID 37644826, 2023). "Subgroup analyses stratified by baseline fibrosis stage, diabetes status, and genetic polymorphisms (particularly PNPLA3, TM6SF2, and HSD17B13 variants) could identify patients most likely to benefit from SGLT2 inhibitor therapy." (PMID 40872510, 2025). "Among patients with HSD17B13 variants, the HCC risk was reduced in those with a FIB‐4 index <2.67, normal body weight, and normal lipid levels; conversely, the HCC risk was increased in patients with diabetes mellitus and hypertension among those with the HSD17B13 A/A genotype." (PMID 37644826, 2023). "The result showed that the protection of HSD17B13 rs72613567 on NASH and fibrosis might be limited to specific individuals who were aged ≥45 years, women who had class ≥2 obesity or diabetes, and those with PNPLA3 rs738409 CC genotype." (PMID 35071330, 2021). "Addition of genetic markers for the prediction of advanced fibrosis (baseline model: age, sex, BMI, diabetes: AUC 0.777) resulted in a higher AUC if PNPLA3(AUC 0.789), and TM6SF2(AUC 0.786) but not if HSD17B13(0.777) were added." (PMID 34076851, 2021).
Obesity (5 papers, 2021 to 2026). Accumulation of substantial excess body fat. "Moreover, we had already determined the reciprocal regulation of Hsd17b13 expression was associated with the simple HFD‐induced obesity beneficial effects of fenretinide." (PMID 40016916, 2025). "Moreover, the reciprocal regulation of Hsd17b13 expression and fibrosis markers was associated with simple HFD‐induced obesity ± beneficial effects of fenretinide (GEO number GSE220684)." (PMID 40016916, 2025). "Hsd17b13 expression, which is unique to hepatocytes and associated with the lipid droplet, was elevated in multiple models of MASLD and normalised with the prevention of obesity and steatotic liver." (PMID 40016916, 2025). "Therefore, HSD17B13 may be an independent protective factor against HCC development, in association with the low‐risk factors of fibrosis and obesity." (PMID 37644826, 2023).
alcoholic liver diseases (4 papers, 2018 to 2022). A disorder caused by damage to the liver parenchyma due to alcohol consumption. "In patients with alcoholic liver disease, the proportion of a loss of function variant (rs72613567) in 17-beta-hydroxysteroid dehydrogenase 13 (HSD17B13) carriers with HCC was significantly lower (32%) than in chronic liver disease patients without HCC (40%)." (PMID 36077080, 2022). "HSD17B13 expression in peritumoral tissues is associated with worse recurrence free survival and overall survival of HCC patients and the HSD17B13 rs72613567 loss of function variant is protective of HCC development in patients with alcoholic liver disease." (PMID 32576292, 2020).
alcoholic cirrhosis (3 papers, 2018 to 2023). "Accurate alcohol history and the addition of genetic testing for PNPLA3 rs738409 and HSD17B13 rs72613567 variants allow our models to increase diagnostic accuracy for compensated alcoholic cirrhosis, with low additional costs." (PMID 37626629, 2023). "The recently identified splice variant rs72613567 in HSD17B13 similarly protects against alcoholic cirrhosis, non-alcoholic cirrhosis and severe liver fibrosis among individuals with hepatitis C." (PMID 32282858, 2020). "Finally, the HSD17B13 rs72613567 variant, in addition to the PNPLA3 rs738409 variant, also allows good accuracy of the prognostic score for the future development of alcoholic cirrhosis to be achieved based on the age of onset of at-risk alcohol consumption." (PMID 37626629, 2023).
Insulin resistance (3 papers, 2020 to 2023). Increased resistance towards insulin, that is, diminished effectiveness of insulin in reducing blood glucose levels. "Emerging evidence supports genetic determinants of FLD (eg PNPLA3, TM6SF2, MBOAT7, GCKR, HSD17B13) as determinants of insulin resistance and T2D." (PMID 33102799, 2020). "Similarly, it is still not known whether the HSD17B13 gene locus influences susceptibility to T2D and insulin resistance." (PMID 33102799, 2020).
dyslipidemia (2 papers, 2021 to 2023). "The incidence of HCC was increased in patients with HSD17B13 A/A in the absence of dyslipidemia (p = 0.03)." (PMID 37644826, 2023).
Hepatitis (2 papers, 2022 to 2025). Inflammation of the liver. "By conducting a comprehensive lipidomic analysis, we identified significant perturbations in hepatic phospholipid metabolism in the Hsd17b13 KO mice, implicating its important role in the pathogenesis of aging-related hepatitis." (PMID 40559377, 2025). "Our data indicate that an HSD17B13 deficiency in mice is accompanied by the development of aging-related hepatitis, without affecting glucose metabolism." (PMID 40559377, 2025).
Hypertension (2 papers, 2023 to 2024). The presence of chronic increased pressure in the systemic arterial system. "Patients with HSD17B13 variants had significantly lower rates of HCC complications (A/A vs. variants; 39 [18.4%] vs. 18 [9.5%], p = 0.01) and hypertension (120 [56.6%] vs. 90 [47.4%], p = 0.06)." (PMID 37644826, 2023).
liver cancer (2 papers, 2020 to 2021). An epithelial or non-epithelial malignant neoplasm that arises from the liver. "We discovered that HSD17B13 rs72613567: TA allelic variant has protective effect on liver cancer: TA vs T OR = 0.649, 95% CI = 0.431–0.977, P = 0.038." (PMID 34930143, 2021). "Using fixed-effect model, we found that patients with HSD17B13 rs72613567: TA allelic variant are less likely to develop liver cancer under allelic model: TA vs T OR = 0.766, 95% CI = 0.682–0.860, P = 0.000." (PMID 34930143, 2021). "The main finding of the present study is the demonstration that specific variants of HSD17B13 and PNPLA3 genes interplay in the determination of genetic predisposition to chronic liver disease progression and liver cancer in HCV-infected subjects." (PMID 32382265, 2020).
viral hepatitis (2 papers, 2021 to 2026). An acute or chronic inflammation of the liver parenchyma caused by viruses. "Well-characterized variants such as PNPLA3, TM6SF2, HSD17B13, and MBOAT7, along with less commonly studied loci and chromosomal alterations, are discussed in relation to major etiologies, including MASLD/MASH, viral hepatitis, alcohol-related liver disease, and autoimmune conditions." (PMID 41590522, 2026).
chronic hepatitis C (1 paper, 2021). "Genetic variants including PNPLA3-rs738409 C>G, TM6SF2-rs58542926 C>T, MBOAT7-rs641738 C>T, and HSD17B13-rs72613567 T>TA have been shown to influence progression to advanced chronic liver disease (ACLD) in patients with chronic hepatitis C (CHC)." (PMID 33917196, 2021).
overnutrition (1 paper, 2021). An imbalanced nutritional status resulting from excessive intake of nutrients. "Overnutrition and sedentary lifestyle have been considered as the main causes of NAFLD and genetic variants, including PNPLA3 rs738409, TM6SF2 rs58542926 and HSD17B13 rs72613567, in patients may accelerate or decelerate the progression of NAFLD." (PMID 33728819, 2021).
prostate carcinoma (1 paper, 2021). A carcinoma that arises from epithelial cells of the prostate gland. "Additionally, Ualcan online database analysis showed increased promoter methylation of both EPB41 and HSD17B13 in prostate cancer patients compared to healthy controls." (PMID 34884649, 2021). "We observed significant hypermethylation in 4 of the 10 target genes (MAN1A1, EPB41, HSD17B13, and MYOM2) in primary prostate cancer patient tumors (n = 503) compared to normal prostatic samples (n = 50) (p ≤ 0.05)." (PMID 34884649, 2021).
tumor (11 papers, 2014 to 2025). "In this study, we for the first time showed that LECT2, SLC10A1, CYP3A4, and HSD17B13 can suppress HCC tumor growth by inhibiting Warburg effect." (PMID 32576292, 2020). "Compared to adjacent normal tissues, tumor tissues exhibited significantly reduced expression of PTGIS, DGKB, HSD17B13, INMT, and ACACB, while PLA2G10, GRHL1, LIPG, and PLA2G4F were markedly upregulated." (PMID 40426878, 2025). "HSD17B13, TM6SF2, PNPLA3, MTARC1, and HLA-DP1 exhibited lower expression in HCC compared with non-tumor liver tissues." (PMID 40823170, 2025). "Our PPI network analysis identified key interactions between HLA-DRB5 and CD244, as well as HSD17B13 and CD244, as potential therapeutic targets in LUAD, with these genes showing downregulation in tumor tissues." (PMID 39092217, 2024).
cancer (6 papers, 2021 to 2025). A tumor composed of atypical neoplastic, often pleomorphic cells that invade other tissues. "HSD17B13, unique to adjacent normal tissue compared to cancer tissue, was enriched in both Specialized Epithelial Cells and Airway Epithelial Cells." (PMID 39092217, 2024). "Inversely, in the liver samples from patients with cancer, HSD17B13 expression was decreased, showing IHC scores of 29.52 ± 3.35, which were consistent with previous reports from patients with HCC." (PMID 35628360, 2022). "ACSL3, AIFM2, HSD17B7, LPCAT1, LSS, PLIN3 and RAB10 were up-regulated with the progression of cancer stage of HCC patients, while CIDEB, G0S2, HSD17B13, PLIN1 and PLIN2 were down-regulated." (PMID 37464334, 2023). "In this context, the potential application of inhibiting HSD17B13 as a therapeutic approach for HCC is currently being investigated, which might be valuable in treating this aggressive cancer." (PMID 40725464, 2025).
infection (2 papers, 2014 to 2022). The state of being infected such as from the introduction of a foreign agent such as serum, vaccine, antigenic substance or organism. "The higher expression of HSD17B13 was directly induced by various factors, including chemical, immunological, fatty, and drug agents, and infections caused by hepatotropic viruses." (PMID 35628360, 2022).
inflammation (2 papers, 2024 to 2025). Aberrant reaction of the microcirculation characterized by movement of fluid and leukocytes from the blood into extravascular tissues. "Investigations in human cohorts have demonstrated that loss-of-function mutations in HSD17B13 gene confer protection against liver inflammation and fibrosis, paradoxically correlating with enhanced lipid deposition." (PMID 39496977, 2024).
HSD17B13 also shares sentences with these, for which no sentence is quoted: metabolic disease (3 papers); Alcohol (2); all (2); liver cirrhosis (2); portal hypertension (2); alcoholic fatty liver disease (1); autoimmune conditions (1); bacterial infection (1); breast carcinoma (1); cardiovascular diseases (1); dyslipidaemia (1); Hepatitis C (1); hyperglycaemia (1); Liver Dysfunction (1); lung carcinoma (1); neuroblastoma (1); non-alcoholic fatty liver (1); pancreatic diseases (1); type 2 diabetes (1); Wilson disease (1).